REN (renin)
Diseases named in the same sentence as REN in open-access papers (continued):
Sharing a sentence is not in itself a finding about the gene and the disease.
COVID-19 (continued). "ACEIs and ARBs act on the renin–angiotensin–aldosterone system (RAAS) reducing angiotensin II formation and consequently downregulating ACE2 expression and probably reducing binding of SARS-COV-2 into the kidney cells and protecting against the development of AKI in COVID-19 patients." (PMID 36859175, 2023). "Due to reports showing that inhibitors of the renin–angiotensin system, including both classes of drugs, might increase ACE2 expression, there were initial concerns that they might influence the severity of COVID-19." (PMID 35163923, 2022). "The renin-angiotensin system in subjects with and without COVID-19." (PMID 33909683, 2021). "It has been hypothesized that in the initial phase of SARS-CoV-2 infection, a RAS imbalance with increased activation of the classical RAS arm (i.e., renin/ACE/angiotensin II axis) leads to alterations in hemostasis and a hyperinflammatory state, triggering COVID-19." (PMID 34945736, 2021). "In addition, we use 50,821 patient records to find that renin–angiotensin–aldosterone system inhibitors have a protective effect for severe COVID-19 outcomes, unlike similar drugs." (PMID 33712587, 2021). "An additional and critical calcitriol action against COVID-19 is the induction of ACE2, which the downregulation by SARS-CoV-2 exacerbates the adverse impact on the lungs of the excessive inflammatory response, initiated by the high activity of the renin–angiotensin II system." (PMID 34444716, 2021). "Although for many scientists this fact could result in an adverse effect of interferon treatment in COVID-19 patients, ACE2 expression contributes to the balance of the renin-angiotensin system, which is greatly affected by SARS-CoV-2 in its internalization into the cell." (PMID 33841439, 2021). "In this line, activation of the non-canonical pathway of the renin-angiotensin-aldosterone system (RAAS) could improve CV homeostasis under COVID-19." (PMID 32899833, 2020). "In addition to COVID-19, orexin A, substance P, bradykinin, and DABK, and the complex interplay between the renin–angiotensin system and the orexinergic system may also have implications for other serious respiratory viral diseases, such as influenza or respiratory syncytial virus." (PMID 40529720, 2025). "As the current pandemic progresses, COVID-19 patients are experiencing a series of nonspecific or atypical extra-pulmonary complications such as systemic inflammation, hypercoagulability state, and dysregulation of the renin–angiotensin–aldosterone system (RAAS)." (PMID 35056603, 2022). "Based on these premises, the possibility of enalkiren to modulate the renin-angiotensin system without altering patient susceptibility to the virus, together with inhibition of the SARS-CoV-2 Mpro, may exhibit beneficial effects for COVID-19 treatment." (PMID 33692695, 2021). "Predictors of mortality in the HF patients infected with COVID-19 were increasing age, male sex, NYHA class, reduced renal function, and patients who did not receive renin–angiotensin system inhibitors." (PMID 34884277, 2021). "Because no loci in ChrX has been genetically associated with severe COVID-19, we interpret that SARS-CoV2 binding and inducing ACE2 degradation may indirectly cause gender difference involving both renal endocrine and immune responses through the renin-angiotensin-aldosterone system (RAAS) axis." (PMID 33233531, 2020). "The negative effect of renin-angiotensin-aldosterone drugs (RAAS) on COVID-19 outcome reported in several studies at the beginning of the pandemic brough attention to a possible relationship between pretreatment with some drug groups and COVID-19 outcome." (PMID 35162123, 2022). "Another report showed that the plasma MMP-2 levels decreased while MMP-9 levels increased in severe COVID-19 patients, but the COVID-19 non-survivors had higher MMP-2 levels than COVID-19 survivors, which is considered to be related to the activation of the renin–angiotensin system." (PMID 35741101, 2022).
COVID-19 (continued). "However, when the renin, ACE-1, and angiotensin receptor inhibitors have been grouped together in studies, this link to COVID-19 severity has not been confirmed." (PMID 33692801, 2021). "In turn, a higher expression of ACE2 may also counteract oxidative stress and inflammation through the role of the receptor in the renin–angiotensin system (RAS), although the significance of this anti-inflammatory mechanism on COVID-19 severity is not well supported by clinical data." (PMID 36680215, 2023).
Obesity (420 papers, 2007 to 2026). Accumulation of substantial excess body fat. "Renin‐angiotensin‐aldosterone system (RAAS) activation mediates obesity‐associated cardiorenal dysfunction." (PMID 41042601, 2026). "It has been postulated that obesity triggers renal hypoxia and hemodynamic disturbances, causing abnormal activation of the renin-angiotensin-aldosterone pathway." (PMID 40557020, 2025). "Obesity and hyperlipidemia can cause excessive activation of the renin-angiotensin-aldosterone system (RAAS), which then causes glomerular hyperfiltration, endothelial and mesangial cell injury and proliferation, and ultimately glomerulosclerosis." (PMID 40959557, 2025). "On the other hand, the lipotoxicity associated with obesity can directly damage myocardial cells and activate the renin-angiotensin system, leading to increased blood pressure and cardiac load." (PMID 41341688, 2025). "Renin–angiotensin–aldosterone system (RAAS) activation is closely linked to obesity; however, the sex-specific associations between RAAS activity and body composition among individuals without obesity are not well understood." (PMID 39148442, 2025). "On the other hand, obesity induces hemodynamic alterations characterized by elevated blood volume, cardiac output, and blood pressure, linked to the activation of the renin-angiotensin-aldosterone system (RAAS) and heightened sympathetic nerve activity." (PMID 40104133, 2025). "Obesity: obesity is associated with increased activation of the renin–angiotensin–aldosterone system (RAAS), leading to sodium retention and volume expansion." (PMID 40053507, 2025). "Obesity is associated with activating the renin–angiotensin–aldosterone axis, which changes the cardiac structure and size." (PMID 38587759, 2024). "Obesity is also linked to hyperactivation of the sympathetic nervous system and the renin–angiotensin–aldosterone system, further contributing to HF development." (PMID 39728435, 2024). "Factors such as insulin resistance, the renin–angiotensin–aldosterone system, systemic inflammation, and sympathetic overdrive contribute to obesity-associated left ventricular dysfunction and remodeling." (PMID 38140337, 2023). "Obesity influences the risk of HT, i.e., through activation of the renin–angiotensin–aldosterone (RAS) system, activation of mineralocorticoid receptors, and activation of the sympathetic nervous system (SNS)." (PMID 37151593, 2023). "Obesity-related cardiovascular diseases are associated with overactivation of the renin-angiotensin system (RAS)." (PMID 37501512, 2023). "Obesity is associated with insulin resistance and over-activity of the renin–angiotensin–aldosterone system, which is related to worse outcomes in COVID-19 infection." (PMID 37373748, 2023). "Insulin resistance caused by obesity will activate the renin-angiotensin-aldosterone system of the body, increase the damage to renal function, and also affect the regulation of uric acid levels by renal function." (PMID 37547098, 2023). "In this review, we focus on the role played by perivascular adipose tissue, the activation of the renin-angiotensin-aldosterone system and endoplasmic reticulum stress in the vascular dysfunction associated with obesity." (PMID 33800427, 2021). "High levels of plasma renin activity, plasma angiotensin, angiotensin II and aldosterone are also associated with obesity." (PMID 33928108, 2021). "In obesity, the renin-angiotensin-aldosterone system (RAAS) is activated, causing amplification of inflammation and structural remodeling, thus inducing cardiac and vascular damage, as well as other structural alterations leading to cardiac dysfunction." (PMID 33809061, 2021). "Obesity-meditated HTN in dogs is associated with elevated renin that is reduced to normal with BAT or the removal of renal nerves." (PMID 34793497, 2021).
Obesity (continued). "The unbalancing effects of natriuretic peptides, neprilysin, and components of renin–angiotensin system, as exacerbating cause of altered adipocytokine signaling on myocardium and vasculature, in obesity patients at high risk of HF are disputed." (PMID 33240938, 2020). "Obesity is associated with adipose tissue dysfunction, which leads to the activation of the renin-angiotensin-aldosterone and sympathetic systems, chronic vascular inflammation, oxidative stress, and inflammation, leading to hypertension." (PMID 31048758, 2019). "In kidney, obesity induces many other risk factors such as hyperinsulinemia, hyperlipidemia, impaired renin angiotensin-aldosterone activity, oxidative stress, and insulin resistance." (PMID 31498850, 2019). "The increased prevalence of obesity and associated comorbidities, such as cardiovascular and metabolic diseases, has gained attention worldwide, and the renin-angiotensin system (RAS) has been pointed out as a possible link." (PMID 31365628, 2019). "Foremost among these is that overweight/obesity is associated with dysfunction of the adipose tissue, which would lead to activation of the renin-angiotensin-aldosterone system, oxidative stress, and chronic vascular inflammation." (PMID 29954383, 2018). "The common independent risk factors are blood pressure and renin-angiotensin-aldosterone system inhibitor use, glycemic control, and anthropometric and laboratory indicators of obesity." (PMID 29254270, 2017). "Nonalcholic fatty liver disease (NAFDL) that often coexists with obesity, also has a significant role both in activating the renin-angiotensin-aldosterone (RAA) system and in causing insulin resistance." (PMID 26980335, 2016). "The pathways linked to the unhealthy obesity were related to vitamin, amino and fatty acid, renin-angiotensin, and sulfur metabolism." (PMID 25866590, 2015). "Obesity is associated with lower levels of plasma renin, epinephrine and high serum levels of low-density lipoproteins that bind circulating lipopolysaccharides." (PMID 26162888, 2015). "In the past decades, multiple studies (in vitro, in vivo, and clinical) indicated the critical role of the renin-angiotensin system (RAS) in the pathogenesis of obesity-associated health disorders." (PMID 23483012, 2013). "Obesity is an important risk factor for the development of hypertensive heart disease due to the associated increase in renin secretion that is mediated by leptin production via adipose cells, resulting in blood pressure elevation and exacerbating already existing hypertension." (PMID 37342440, 2023). "In addition, neurohumoral and metabolic disorders caused by obesity, including increased insulin resistance, activation of the renin–angiotensin–aldosterone system, and autonomic dysfunction, also drive cardiac changes in the structure and function." (PMID 35565843, 2022). "Some studies have demonstrated that both PAC and PRA decreased after weight loss suggesting that obesity may be associated with a systemic stimulation of the renin-angiotensin-aldosterone system." (PMID 34675881, 2021). "In this regard, obesity-induced DD is associated with multiple abnormalities, including inappropriate activation of tissue Renin–Angiotensin–Aldosterone System (RAAS), as well as, normal or subnormal responses to ANP in the early stages of the disease or enhanced ANP responsiveness at later stages." (PMID 33882908, 2021). "Local renal tubular renin-angiotensin system (RAS) activation may play a role in obesity-associated kidney disease." (PMID 34568382, 2021). "Among other factors, obesity-associated activation of the renin-angiotensin-aldosterone system (RAAS), in particular hyperaldosteronism, might contribute to CVD in obese individuals." (PMID 32529242, 2020).
Obesity (continued). "The occurrence of high serum cholesterol, triacylglycerol, and non-esterified fatty acid levels in the OB group can be explained by the chronic intake of lipids and sugar associated with renin-angiotensin system activation and insulin resistance in the obesity condition." (PMID 24466104, 2014). "Another pathway possibly involved in the cardiac impairment associated with obesity may be the renin-angiotensin system." (PMID 23755190, 2014). "The renin-angiotensin system expressed in adipose tissue has been implicated in the modulation of adipocyte formation, glucose metabolism, triglyceride accumulation, lipolysis, and the onset of the adverse metabolic consequences of obesity." (PMID 24098385, 2013). "Furthermore, recent studies have underlined that there are intricate interplays among adipocytes, the sympathetic nervous system and the renin-angiotensin system, which participate in the obesity-associated dysmetabolic state." (PMID 23433085, 2013). "Furthermore, chronic overweight/obesity is associated with hyperactivity of the sympathetic nervous system and renin‐angiotensin‐aldosterone system, which may synergistically accelerate cardiometabolic dysfunction and CMM development." (PMID 41017239, 2025). "Furthermore, obesity may induce aberrations in glomerular hemodynamics and provoke the overactivation of the renin-angiotensin-aldosterone system, potentially leading to obesity-associated nephropathy." (PMID 38254222, 2024). "In addition, obesity was often accompanied by hyperinsulinemia, which could cause increased sympathetic tone and activate the renin‐angiotensin system, resulting in increased HR." (PMID 38599825, 2024). "Future perspectives: Future studies should focus on evaluating the individual evolution of urinary EGF, renin and blood pressure under the influence of weight loss in children and adolescents with obesity, or the effect of physical exercise in both children and adolescents with obesity or T1DM." (PMID 36996194, 2023). "NAFLD and CKD seem to share important obesity-associated metabolic risk factors, and these two diseases may be driven commonly by obesity-associated mechanisms including lipotoxicity, oxidative stress, enhanced proinflammatory cytokines, and renin-angiotensin-aldosterone system (RAAS) activation." (PMID 29808087, 2018). "In addition, obesity could cause leptin resistance and increase activity of the renin-angiotensin-aldosterone system, which ultimately cause increased peripheral vascular resistance and elevated blood pressure." (PMID 27663794, 2016). "Lower systemic vascular resistance, plasma renin activity and renin-angiotensin responses, lower levels of atrial natriuretic peptides, and an attenuated sympathetic nervous system are pathophysiological changes in obese patients that can balance the risk that obesity itself represents." (PMID 25781994, 2015). "NAFLD and CKD share common risk factors and therefore both liver and kidney injury may be driven by obesity-associated mechanisms of disease, including lipotoxicity, oxidative stress, enhanced pro-inflammatory cytokine, and renin-angiotensin-aldosterone system (RAAS) axis activation." (PMID 25050550, 2014). "Mechanistically, obesity promotes left-atrial enlargement, epicardial adipose deposition, low-grade inflammation, and renin–angiotensin–aldosterone activation, all of which favour atrial ectopy and re-entry." (PMID 41598515, 2026). "Obesity also alters the renin–angiotensin–aldosterone system, leading to sodium retention and volume expansion." (PMID 40150467, 2025). "This is explained by the activation of the renin-angiotensin and sympathetic nervous systems and the occurrence of obstructive sleep apnea in obesity." (PMID 39897192, 2025). "Although the majority of the existing literature supports predominantly renin-dependent aldosteronism in obesity, evidence among patients with primary aldosteronism also supports a link of renin-independent aldosteronism to obesity." (PMID 39148442, 2025).